CACNA1H (calcium voltage-gated channel subunit alpha1 H)
Description:
Voltage-sensitive calcium channel that gives rise to T-type calcium currents. T-type calcium channels belong to the 'low-voltage activated (LVA)' group. A particularity of this type of channel is an opening at quite negative potentials, and a voltage-dependent inactivation. T-type channels serve pacemaking functions in both central neurons and cardiac nodal cells and support calcium signaling in secretory cells and vascular smooth muscle (Probable). They may also be involved in the modulation of firing patterns of neurons. In the adrenal zona glomerulosa, participates in the signaling pathway leading to aldosterone production in response to either AGT/angiotensin II, or hyperkalemia.
Synonyms: Cav3.2; CACNA1HB; ECA6; EIG6; HALD4
Tractability: Small molecule: an approved drug acts on it; a structure with a bound ligand is known; a high-quality ligand is known; it belongs to a druggable protein family. Antibody: UniProt places it where antibodies can reach, with high confidence; its Gene Ontology location is reachable by antibodies, with high confidence; UniProt predicts a signal peptide or a membrane-spanning region. PROTAC: ubiquitination databases record sites on it; its protein half-life has been measured; a small molecule that binds it is known.
Target class: Voltage-gated calcium channel; Ion channel; Voltage-gated ion channel
Chemical probes: CHEMBL1210766, ML218
Gene: Protein-coding gene on chromosome 16 (1,153,103 to 1,224,169, forward strand). Ensembl gene ENSG00000196557.
Subcellular location: Cell membrane
Subcellular location (Human Protein Atlas): Nucleoplasm; Vesicles
Pathways (Reactome):
Cellular responses to stimuli: Mechanical load activates signaling by PIEZO1 and integrins in osteocytes
Developmental Biology: NCAM1 interactions
Muscle contraction: Smooth Muscle Contraction
Gene Ontology:
Molecular function: low voltage-gated calcium channel activity; protein binding; scaffold protein binding; voltage-gated calcium channel activity; voltage-gated monoatomic ion channel activity; high voltage-gated calcium channel activity; monoatomic ion channel activity
Biological process: aldosterone biosynthetic process; calcium ion import; cellular response to hormone stimulus; cellular response to potassium ion; cortisol biosynthetic process; positive regulation of acrosome reaction; regulation of membrane potential; transmembrane transport; calcium ion import across plasma membrane; muscle contraction; muscle organ development; myoblast fusion; regulation of heart contraction; calcium ion transmembrane transport; monoatomic ion transport
Cellular component: membrane; plasma membrane; voltage-gated calcium channel complex
Genetic constraint (gnomAD): Loss-of-function variants: 149 observed, 161.13 expected, observed/expected ratio (o/e) 0.92, 90% interval 0.81 to 1.06. The synonymous counts are far from expectation, so gnomAD's model fits this gene poorly and the ratio says little. Missense variants: 4,250 observed, 3,086.7 expected, observed/expected ratio (o/e) 1.38, 90% interval 1.34 to 1.41. Synonymous variants: 2,202 observed, 1,338.2 expected, observed/expected ratio (o/e) 1.65, 90% interval 1.59 to 1.7.
Homologues: Orthologues: macaque CACNA1H (96% identical), chimpanzee CACNA1H (94% identical), rat Cacna1h (85% identical), mouse Cacna1h (85% identical), guinea pig CACNA1H (83% identical), dog CACNA1H (82% identical), pig CACNA1H (82% identical), tropical clawed frog cacna1h (64% identical), zebrafish cacna1hb (45% identical). Paralogues in human: CACNA1G (55% identical), CACNA1I (53% identical), CACNA1B (23% identical), CACNA1A (22% identical), CACNA1D (22% identical), CACNA1C (21% identical), CACNA1F (21% identical), CACNA1E (21% identical), CACNA1S (20% identical), SCN2A (19% identical), SCN3A (19% identical), SCN8A (19% identical), and 14 more.
Diseases named in the same sentence as CACNA1H in open-access papers:
CACNA1H is named in the same sentence as 137 diseases in open-access papers, as found by Europe PMC text mining. Sharing a sentence is not in itself a finding about the gene and the disease. The quoted sentences say what the papers report.
epilepsy (57 papers, 2007 to 2026). A brain disorder characterized by episodes of abnormally increased neuronal discharge resulting in transient episodes of sensory or motor neurological dysfunction, or psychic dysfunction. "A total of nine SNPs in the CACNA1A, CACNA1C, and CACNA1H genes were selected based on their reported associations with neurodevelopmental disorders and epilepsy." (PMID 40725423, 2025). "This study aims to address this gap by investigating the frequency of selected SNPs in CACNA1A, CACNA1C, and CACNA1H in Korean children with DD/ID, and by evaluating their association with epilepsy comorbidity." (PMID 40725423, 2025). "The second top DhMR was found in CACNA1H, which encodes a protein in a voltage-dependent calcium channel complex that has been implicated in epilepsy." (PMID 37139321, 2023). "Mutations on CACNA1H was previously reported in epilepsy patients by influencing neuronal excitatory." (PMID 37747131, 2023). "As for CACNA1G, CACNA1H variants should be considered a risk factor for developing epilepsy, most likely implicating other genetic and/or environmental factors." (PMID 32638069, 2020). "Here, we characterized the functional effects of two missense variants identified in the CACNA1H gene from a patient with epilepsy." (PMID 31651342, 2019). "While some prior studies have suggested a role of rare gain of function mutations in CACNA1H in epilepsy, these studies have not approached genome-wide levels of significance, do not appear to confer high risk, and have not been uniformly replicated." (PMID 25907736, 2015). "Similarly, CACNA1H variants have been linked to various epilepsy subtypes, particularly childhood absence epilepsy." (PMID 40725423, 2025). "Despite this, CACNA1H variants were included in this analysis to provide a comprehensive overview of all identified variants, given their potential role in seizure susceptibility and frequent detection in epilepsy cohorts." (PMID 39906551, 2024). "For instance, although different variants in CACNA1H have been reported in patients with congenital forms of idiopathic generalized epilepsies (IGEs) or absence epilepsy, their classification as pathogenic variants and the association of CACNA1H with epilepsy has been questioned." (PMID 37047073, 2023). "Recently, Algahtani and colleagues reported a new heterozygous missense mutation in a 50-year-old female patient with a clinical condition involving epilepsy and hearing loss which appears to be the first CACNA1H variant to be associated with sensorineural hearing alterations." (PMID 37735453, 2023). "Mutations in several other regulators identified in our screen may also result in antibody immunodeficiency, including CACNA1H, a calcium channel linked to epilepsy." (PMID 36860866, 2023). "CACNA1H encodes a low-voltage-activated calcium channel, which is expressed in thalamocortical circuits and is involved in the formation of neuronal burst firing and rhythm generation, as well as sleep and the development of epilepsy." (PMID 37250140, 2023). "Since only one of the twins of family 22 had fever triggered epilepsy, we might hypothesize that CACNA1H variants could also contribute to epilepsy, but with variable penetrance." (PMID 35350424, 2022). "Furthermore, mutations within the CACNA1H gene encoding CaV3.2 have been associated with several forms of epilepsy." (PMID 35209100, 2022). "Despite having been reported animal models carrying Cacna1h mutations that cosegregate with epilepsy phenotypes, in humans heterozygous mutations have been only associated with susceptibility to generalized epilepsy and focal or multifocal epilepsy and DEEs of varying severity." (PMID 35328054, 2022). "Indeed, gain-of-function mutations in the CACNA1H gene via signalling Ca2+-regulated transcription factors disrupt neuronal development, resulting in an increase in seizure susceptibility in epilepsy patients." (PMID 34573310, 2021).
epilepsy (continued). "CACNA1H pathogenic variants have been associated with multiple disorders, including aldosteronism, autism, amyotrophic lateral sclerosis, but is predominantly associated with epilepsy." (PMID 31651342, 2019). "In addition, a very small partial 16p13.3 duplication was found including the CACNA1H gene encoding a calcium ion channel subunit, causing susceptibility to epilepsy." (PMID 25400949, 2014). "KDM5C gene silencing leads to down-regulation of SCN2A, CACNA1B; CACNA1H; SCL4A3, SLC18A1, and SLC6A12, All of these KDM5C target genes have been linked to neurological disorders such as epilepsy, autism or schizophrenia." (PMID 39948613, 2025). "This study focused specifically on three voltage-gated calcium channel genes—CACNA1A, CACNA1C, and CACNA1H—due to their well-established roles in neurodevelopmental disorders and epilepsy." (PMID 40725423, 2025). "Transcriptomic analyses of cultured fibroblasts in three healthy and six epileptic seizure minipigs have revealed a potential role for differential expression of CACNA1H in epilepsy." (PMID 38383918, 2024). "This also underscored the importance of refining gene classifications to clarify the precise role of CACNA1H in epilepsy through further functional studies and larger cohort analyses." (PMID 39906551, 2024). "This review delves into the significance of the CACNA genes, including CACNA1A, CACNA1B, CACNA1C, CACNA1D, CACNA1E, CACNA1G, and CACNA1H, in the pathogenesis of conditions such as migraine, epilepsy, cerebellar ataxia, dystonia, and cerebellar atrophy." (PMID 38785745, 2024). "For example, in our cohort, two children with intractable post-neonatal epilepsy had variants in the CASK and CACNA1H genes." (PMID 33846556, 2022). "In another review, both gain- and loss-of-function variants in CACNA1A, gain-of-function variants in CACNA1H, and variants in CACNA1G were linked to epilepsy." (PMID 33985586, 2021). "As such, the present study suggests that arginine 788 in CACNA1H is an important contributor to epilepsy." (PMID 29924869, 2018). "For example, the following genes were previously thought to be associated with epilepsy: EFHC1, SCN9A, CLCN2, GABRD, SRPX2 and CACNA1H." (PMID 28558813, 2017). "The role of voltage-gated channels in the activity of neuronal excitability indicates that mutations in Ca2+ channel genes CACNA1A, CACNA1H, CACNA2D2, and CACNB4 might be associated with the occurrence of epilepsy." (PMID 38383918, 2024). "Pathogenic variants in CACNA1H are associated with autism and epilepsy, which the patient did not have." (PMID 34816733, 2021). "Other studies show that variation in another calcium channel gene CACNA1H contributes to the pathogenesis of complex epilepsy such as congenital absence epilepsy, but no variants have been described to cause epilepsy on its own." (PMID 25893123, 2015). "Three types of T-type calcium channels consisting of Cav3.1, Cav3.2, and Cav3.3 are encoded by CACNA1G, CACNA1H, and CACNA1I genes, respectively, which are expressed in the brain and play essential roles in both physiological and pathological systems, including sleep, pain, and epilepsy." (PMID 34201181, 2021). "In other words, CACNA1H variants are not causing monogenic epilepsy." (PMID 32638069, 2020). "Although none of the variants found in the human CACNA1H gene so far are sufficiently pathogenic to cause epilepsy on their own, a change may act in combination with other variants or environmental factors to force the level of neuronal excitability above the seizure threshold." (PMID 35328054, 2022). "The CACNA1H gene, as CACNA1G, has received much attention regarding its potential implication in inherited epilepsy phenotypes." (PMID 32638069, 2020).
epilepsy (continued). "Several other genes that we have identified as undergoing mTLE-linked alternative splicing events also have been associated with other, non-mTLE forms of human epilepsy, including CACNA1A, CACNA1H, CLCN2, and GABRG2, indicating that these also may be of particular interest in the epilepsy field." (PMID 17343748, 2007). "However, so far the association of most genetic variants in CACNA1G and CACNA1H and their functional mechanism of action in terms of GOF or LOF for idiopathic genetic epilepsies is less well understood and mutations in Cav3.1 or Cav3.2 causing high risk for epilepsy have not been described." (PMID 33746731, 2021).
autism (14 papers, 2011 to 2026). Persistent deficits in social interaction and communication and interaction as well as a markedly restricted repertoire of activity and interest as well as repetitive patterns of behavior. "Apart from potassium, some prominent calcium channels (Cacna1e and Cacna1h) and sodium (Scn3b) channels, which are implicated in autism and epilepsy, are also enriched." (PMID 37845544, 2023). "Recently, we have identified in one Brazilian individual with autism and macrocephaly rare compound heterozygous missense variants in the RELN gene and a de novo splice site variant in the CACNA1H gene." (PMID 35668055, 2022). "The third variant, CACNA1H, is a gene associated with autism and generalized absent seizures, which were not suggested by medical history." (PMID 34816733, 2021). "The Cacna1h gene is registered as a strong candidate in the autism-related gene database, SFARI." (PMID 27782041, 2016).
autism spectrum disorder (12 papers, 2012 to 2025). A spectrum of developmental disorders that includes autism, and Asperger syndrome. "Studies have found that CACNA1H mutations exist in childhood absence epilepsy, generalized epilepsy with febrile seizures plus, and autism spectrum disorders, suggesting that CACNA1H plays an important role in neurological lesions." (PMID 37250140, 2023). "Rare missense mutations in CACNA1H were found in 6 of 461 individuals with autism spectrum disorder." (PMID 26386135, 2015). "Indeed, specific missense variants in CACNA1H have been implicated in a range of human conditions, including autism spectrum disorders and amyotrophic lateral sclerosis." (PMID 36786913, 2023). "Furthermore, mutations of the human CACNA1H gene coding for Cav3.2 have been associated with autism spectrum disorders (ASDs)." (PMID 35408817, 2022). "Epileptic syndromes caused by CACNA1H defects include a variety of neurodevelopmental disorders and the authors tried to identify the genotypic associations in different phenotypes, including autism spectrum disorder (ASD), immunoglobulin-E (IgE), and neuromuscular disorders." (PMID 36090251, 2022). "Mutations of human ortholog of the Cav3.2 gene, CACNA1H, are associated with childhood absence epilepsy (CAE) and autism spectrum disorder (ASD)." (PMID 22235292, 2012). "Several genes were validated in APA sperm that were associated with autism spectrum disorder (CACNA1H, CNTNAP2, GRIN1, SHANK2, SHANK3, ZNF804A), schizophrenia (TCF3, ZNF804A), and bipolar disorder (COMT, DRD4, GRIN1, MBP, PRKCZ, SHANK2, TRPM2, ZNF804A), and in APA blastocysts (CACNA1H)." (PMID 32610362, 2020).
breast carcinoma (12 papers, 2014 to 2025). "Consistent with Prof. Pera, we found that CACNA1H had high expression and high mutation rate in breast cancer." (PMID 36277284, 2022). "As the cellular antenna for breast cancer-specific frequencies, CACNA1H mediates the targeted inhibition of breast cancer brain metastasis." (PMID 37250140, 2023). "CACNA1H is a voltage gated calcium channel whose expression was found to positively correlate with a decrease in brain metastasis in the breast cancer PDX model." (PMID 36474139, 2022). "Conversely, AK3 and CACNA1H are suggested to exert inhibitory effects on breast cancer progression." (PMID 39590319, 2024). "We developed a novel GRG signature of six GRGs, including CACNA1H, CHPF, IRS2, NT5E, SDC1 and ATP6AP1, to predict survival and guide individual therapy in breast cancer." (PMID 36277284, 2022). "However, in the TNBC subtype, we observed an opposite expression pattern: CACNA1H and KCNJ11 were significantly downregulated compared to other breast cancer subtypes, whereas S100B showed markedly elevated expression." (PMID 40606662, 2025). "We found that the protein levels of CACNA1H, CHPF, SDC1 and ATP6AP1 were higher in breast cancer tissues compared with normal tissues, while the expression levels of IRS2 and NT5E were comparatively lower in breast cancer tissues, and the expression of them is consistent with mRNA level." (PMID 36277284, 2022). "Breast cancers with high levels of CACNA1H (Cav3.2) (2nd, 3rd, 4th quartile) showed a significant elevation in levels of ESR1 and PGR compared to breast cancers with significantly low levels of Cav3.2 (1st quartile)." (PMID 27034617, 2016).
generalized epilepsy (12 papers, 2016 to 2025). Epilepsy that is characterized by generalized seizure types and may have typical interictal and/or ictal EEG findings that accompany generalized seizure types (for example generalized spike-wave). "Mutations in the Cav3.1-encoding gene CACNA1G and Cav3.2-encoding gene CACNA1H are associated with idiopathic generalised epilepsies in humans." (PMID 37082241, 2023). "Many missense variants in the human CACNA1H gene have been reported in patients presenting with a range of epilepsy syndromes, so the gene was labelled a risk gene for idiopathic generalised epilepsies." (PMID 36786913, 2023). "A number of missense mutations have been identified in CACNA1H in subjects with different types of generalized epilepsy that include: febrile, myoclonic, temporal lobe, and childhood and juvenile absence epilepsies." (PMID 31651342, 2019). "Two paternally-inherited missense variants in CACNA1H were identified and characterized in a 6-year-old child with generalized epilepsy." (PMID 31651342, 2019). "Gain-of-function mutations in CACNA1H (Cav3.2) channels have been found in various forms of idiopathic generalized epilepsies, such as absence epilepsy." (PMID 27242528, 2016). "Polymorphisms in the CACNA1H gene have been reported in a number of human disorders and GoF mutations in Cav3.2 are linked to primary aldosteronism (PA) and idiopathic generalized epilepsy (IGE)." (PMID 36397158, 2022).
Hypertension (11 papers, 2009 to 2026). The presence of chronic increased pressure in the systemic arterial system. "CACNA1H is associated with hypertension and is therapeutically targetable by calcium channel blockers." (PMID 32898326, 2020). "While germline mutations in KCNJ5 and CACNA1D were discovered following the initial identification of their somatic mutations in APAs, the discovery of the recurrent CACNA1H mutation relied entirely on brute force sequencing of patients with early severe aldosteronism and hypertension." (PMID 25907736, 2015). "The apparent limitation of the phenotype associated with CACNA1HM1549V to PA with hypertension despite the expression of CACNA1H in other organs including heart and brain is notable, and underscores the challenges in predicting human phenotypes from knowledge of underlying mutations." (PMID 25907736, 2015). "Additionally, mutations in CACNA1H, a gene encoding the α subunit of CaV3.2 have been identified in APA and could be the cause of early-onset hypertension with primary aldosteronism." (PMID 35197862, 2022). "Studies showed that biomarkers include PLD2, FLNA (filamin A), SMURF1, LINGO1, CACNA1H, NLRP6, NLRC3, CXCR2 and C5AR1 plays an important role in progression of hypertension." (PMID 36837510, 2023).